TEKT5 (tektin 5)
Description:
Sperm-specific microtubule inner protein (MIP) part of the dynein-decorated doublet microtubules (DMTs) in flagellar axoneme. Forms an extensive interaction network in different conformations that reinforces the helix bundle composed by other tektin proteins (TEKT1 to TEKT4) and MIPs to anchor the tektin bundle onto the tubulin wall of A-tubule of the sperm flagellum.
Synonyms: FLJ32871; CT149
Tractability: PROTAC: UniProt records ubiquitination sites on it.
Gene: Protein-coding gene on chromosome 16 (10,627,501 to 10,694,930, reverse strand). Ensembl gene ENSG00000153060.
Subcellular location: Cytoplasm, cytoskeleton, flagellum axoneme
Subcellular location (Human Protein Atlas): Actin filaments
Gene Ontology:
Molecular function: protein binding
Biological process: cilium assembly; cilium movement involved in cell motility; flagellated sperm motility
Cellular component: nucleus; axonemal A tubule inner sheath; microtubule cytoskeleton; sperm flagellum; cilium; cytoplasm
Genetic constraint (gnomAD): Loss-of-function variants: 54 observed, 51.35 expected, observed/expected ratio (o/e) 1.05, 90% interval 0.84 to 1.32. The upper end of that interval is the gene's LOEUF score, 1.32, which puts it in group 5 of 6, group 1 being the genes least tolerant of losing a copy. Missense variants: 831 observed, 669.06 expected, observed/expected ratio (o/e) 1.24, 90% interval 1.17 to 1.32. Synonymous variants: 318 observed, 281.33 expected, observed/expected ratio (o/e) 1.13, 90% interval 1.03 to 1.24.
Homologues: Orthologues: chimpanzee TEKT5 (98% identical), macaque TEKT5 (96% identical), dog TEKT5 (89% identical), pig TEKT5 (87% identical), rabbit TEKT5 (87% identical), mouse Tekt5 (83% identical), rat Tekt5 (83% identical), guinea pig TEKT5 (73% identical), Drosophila melanogaster CG17450 (35% identical), Drosophila melanogaster CG32819 (35% identical), Drosophila melanogaster CG32820 (35% identical). Paralogues in human: TEKT3 (49% identical), TEKT4 (30% identical), TEKT1 (30% identical), TEKT2 (25% identical), MAFIP (10% identical).
Diseases named in the same sentence as TEKT5 in open-access papers:
TEKT5 is named in the same sentence as 17 diseases in open-access papers, as found by Europe PMC text mining. Sharing a sentence is not in itself a finding about the gene and the disease. The quoted sentences say what the papers report.
breast carcinoma (1 paper, 2025). "Pre-mRNA mutations in Tekt1, Tekt4, and Tekt5 are strongly correlated with the occurrence of civil dyskinesia, breast cancer, and coronary artery disease, respectively." (PMID 39949046, 2025). "Individual Tekt proteins may also play distinct roles in specific biological processes, such as Tekt2 in photoreceptor survival, Tekt4 in breast cancer, and Tekt5 in sperm formation and cancer cell survival." (PMID 39949046, 2025).
colon cancer (1 paper, 2012). "In malignant tissues, TEKT5 mRNA expression was detected in 5 of 10 colon cancers, 4 of 10 gastric cancers, 6 of 10 liver cancers, 1 of 10 lung cancers, and 1 of 9 prostate cancers at >1% of the testicular expression level." (PMID 23151147, 2012). "A serological survey of 101 cancer patients with different cancers by ELISA revealed antibodies to TEKT5 in 13 patients, including colon cancer." (PMID 23151147, 2012). "By cDNA microarray analysis, TEKT5 showed higher expression levels in 2 of 3 colon cancer tissues compared with normal tissue." (PMID 23151147, 2012). "In this study, we performed SEREX analysis of colon cancer, and isolated a novel CT antigen, Tektin5 (TEKT5), in addition to a previously defined CT-like antigen, A kinase anchoring protein 3 (AKAP3)." (PMID 23151147, 2012). "4/44 sera from colon cancer patients, 6/15 sera from liver cancer patients, and 3/19 sera from head & neck cancer patients were reactive against TEKT5." (PMID 23151147, 2012). "In malignant tissues, TEKT5 was aberrantly expressed in a variety of cancers, including colon cancer." (PMID 23151147, 2012). "We isolated human TEKT5, and showed that it has the characteristics of a CT antigen and that it elicits a strong immune response in a subset of patients with cancer, including colon cancer." (PMID 23151147, 2012). "TEKT5 expression was highly up-regulated in 2 colon cancer specimens (3.55- and 7.96-fold)." (PMID 23151147, 2012). "We identified candidate new CT antigen of colon cancer, TEKT5." (PMID 23151147, 2012).
coronary artery disease (1 paper, 2025). "A study reported that the top GWAS hits associated with all-cause mortality among people with coronary artery disease included 1 SNP (rs9932462, Tekt5) among 510 males." (PMID 39949046, 2025).
lung carcinoma (1 paper, 2012). "No TEKT5 antibody was detected in the sera from 23 lung cancer patients." (PMID 23151147, 2012).
ovarian carcinoma (1 paper, 2025). A malignant neoplasm originating from the surface ovarian epithelium. "In ovarian cancer cells, Tekt5 knockdown has been shown to induce G1 arrest and apoptosis by upregulating p27kip1 (a cyclin-dependent kinase inhibitor)." (PMID 39949046, 2025). "Furthermore, the role of Tekt4 in thyroid tumourigenesis and the influence of Tekt5 on cell cycle regulation in ovarian cancer cells highlight a significant connection between Tekt proteins and the development of cancer." (PMID 39949046, 2025).
cancer (2 papers, 2012 to 2025). A tumor composed of atypical neoplastic, often pleomorphic cells that invade other tissues. "The findings indicate that TEKT5 is immunogenic in humans, and suggest its potential use as diagnostic as well as a immunotherapeutic reagent for cancer patients." (PMID 23151147, 2012). "Taken together, the findings suggest that serologically defined TEKT5 provides a molecular basis for diagnostic and immunotherapeutic targets in cancer patients." (PMID 23151147, 2012). "The findings indicate that TEKT5 is immunogenic in humans, and suggest its potential use as diagnostic as well as an immunotherapeutic reagent for cancer patients." (PMID 23151147, 2012). "In our survey of 101 cancer patients with several types of cancer, 13 patients produced antibody to TEKT5 protein." (PMID 23151147, 2012). "Sera from 101 cancer patients and 16 healthy donors were tested for IgG antibody by ELISA using recombinant TEKT5 protein." (PMID 23151147, 2012).
TEKT5 also shares sentences with these, for which no sentence is quoted: infection (2 papers); influenza (2); gastric cancer (1); head & neck cancer (1); Insulin resistance (1); liver cancer (1); male infertility (1); Obesity (1); prostate carcinoma (1); pulmonary diseases (1); skin cutaneous melanoma (1).